ENSG00000252601
Synonyms: LOC124900206
Gene: Small nucleolar RNA gene on chromosome 5 (29,070,496 to 29,070,610, forward strand). Ensembl gene ENSG00000252601.
Gene Ontology:
Biological process: RNA processing
Cellular component: nucleolus
Homologues: Paralogues in human: SNORA18 (79% identical).